KIF22 (kinesin family member 22)
Diseases named in the same sentence as KIF22 in open-access papers (continued):
Sharing a sentence is not in itself a finding about the gene and the disease.
melanoma (1 paper, 2023). A malignant, usually aggressive tumor composed of atypical, neoplastic melanocytes. "In this study, the authors discovered that KIF22 was overexpressed in melanoma tissue and high KIF22 expression was positively associated with lower overall survival according to the Tnmplot database." (PMID 37944197, 2023). "KIF22 expression was notably upregulated in melanoma tissues and cells, and KIF22 high expression was associated with a poor prognosis." (PMID 37944197, 2023). "Collectively, KIF22 knockdown suppressed the proliferation and glycolysis and facilitated the apoptosis of melanoma cells by inactivating EGFR/STAT3 signaling." (PMID 37944197, 2023). "Particularly, KIF22 is required for the invasion of melanoma cells, and the knockdown of KIF22 inhibits the invasion of melanoma cells." (PMID 37944197, 2023). "Summing up, KIF22 depletion represses proliferation, inhibits glycolysis, and accelerates apoptosis of melanoma cells by inactivating EGFR/STAT3 signaling." (PMID 37944197, 2023). "The effects of KIF22 insufficiency on the proliferation and glycolysis in melanoma cells were analyzed." (PMID 37944197, 2023). "Collectively, these results imply the inhibitory role of KIF22 knockdown on tumor glycolysis in melanoma cells." (PMID 37944197, 2023). "KIF22 expression in melanoma tissues and the relationship between KIF22 high expression and overall survival rate in patients with melanoma were analyzed using the Tnmplot database." (PMID 37944197, 2023). "In this study, KIF22 expression in melanoma tissues and the correlation between KIF22 expression and prognosis were assessed by bioinformatics tools." (PMID 37944197, 2023). "Of note, the authors also demonstrated for the first time that KIF22 insufficiency suppressed the proliferation of melanoma cells." (PMID 37944197, 2023). "In this work, KIF22 interference notably repressed glycolysis in melanoma cells, evidenced by reduced levels of ECAR, lactate production, HK2, PKM2 and LDHA expression as well as elevated levels of OCR." (PMID 37944197, 2023). "Subsequently, melanoma cells were treated with EGF or Colivelin to further elucidate the regulatory effect of KIF22 on EGFR/STAT3 signaling." (PMID 37944197, 2023). "Taken together, the present study is the first to demonstrate that KIF22 knockdown suppresses the proliferation and glycolysis and facilitates the apoptosis of melanoma cells by inactivating EGFR/STAT3 signaling." (PMID 37944197, 2023). "•KIF22 depletion suppresses proliferation, glycolysis and facilitates apoptosis of melanoma cells by inactivating EGFR/STAT3 signaling." (PMID 37944197, 2023). "Consistently, the EDU fluorescence intensity in A375 cells was prominently diminished in the siRNA-KIF22-1 group relative to the siRNA-NC group, suggesting the inhibitory effect of KIF22 knockdown on the proliferation of melanoma cells." (PMID 37944197, 2023). "Kinesin Family member 22 (KIF22) is essential for the invasion of melanoma cells, but the role and mechanism of KIF22 in the proliferation and glycolysis in melanoma remains unknown." (PMID 37944197, 2023). "KIF22 expression in melanoma cells was examined by western blot." (PMID 37944197, 2023). "Importantly, the impacts of KIF22 depletion on the progression of melanoma were partially attenuated after EGF or Colivelin treatment." (PMID 37944197, 2023). "The present study demonstrated that KIF22 was upregulated in melanoma tissues and cells." (PMID 37944197, 2023). "•KIF22 knockdown inhibits tumor glycolysis in melanoma cells." (PMID 37944197, 2023). "•KIF22 expression is upregulated in melanoma tissues and cells." (PMID 37944197, 2023). "The authors revealed for the first time that KIF22 depletion could restrain proliferation, glycolysis and accelerate apoptosis of melanoma cells by inactivating EGFR/STAT3 signaling." (PMID 37944197, 2023). "•KIF22 knockdown suppresses proliferation and facilitates apoptosis of melanoma cells." (PMID 37944197, 2023).
melanoma (continued). "Therefore, the authors hypothesized that KIF22 might affect the proliferation and glycolysis of melanoma cells by regulating EGFR/STAT3 signaling." (PMID 37944197, 2023). "Moreover, KIF22 insufficiency suppressed proliferation and accelerated apoptosis of melanoma cells." (PMID 37944197, 2023). "It has been reported that KIF22 can activate Epidermal Growth Factor Receptor (EGFR) signaling, an effective target for melanoma." (PMID 37944197, 2023). "It has been reported that KIF22 activates EGFR signaling, an effective target for melanoma." (PMID 37944197, 2023). "So far, the effects of KIF22 on the proliferation and glycolysis of melanoma cells have not been investigated." (PMID 37944197, 2023). "Additionally, a western blot was used to assess KIF22 expression in various melanoma cell lines (SK-MEL-1, SK-MEL-28, A375 and MeWo) and the normal Human Epidermal Melanocytes (HEM)." (PMID 37944197, 2023).
Spondyloepimetaphyseal dysplasia with joint laxity, type 2 (1 paper, 2026). "Spondyloepimetaphyseal dysplasia with joint laxity, type 2 (SEMDJL2) is a rare skeletal disorder caused by pathogenic variants in KIF22, a mitotic chromokinesin that generates polar ejection forces (PEF) to ensure proper chromosome alignment and segregation." (PMID 41959455, 2026).
cancer (15 papers, 2017 to 2025). A tumor composed of atypical neoplastic, often pleomorphic cells that invade other tissues. "However, studies have revealed that KIF22 is overexpressed in many cancers and associated with poor prognosis." (PMID 38713252, 2024). "The alteration of KIF22 is associated with several cancers, including CRC." (PMID 37686578, 2023). "In cancer cells, inhibition of KIF22 leads to a G2/M phase accumulation and disrupted cell cycle progression." (PMID 38989461, 2024). "KIF22’s role as a mitogenic factor also links it to cancer cell proliferation." (PMID 38989461, 2024). "Although functional studies examining the role of KIF22 in proliferation have been conducted in cancer cells, the role of Kif22 in chondrocytes remains unknown." (PMID 38989461, 2024). "KIF22, as a member of KIFs, has been reported to be of high expression in a number of cancers." (PMID 38713252, 2024). "As an oncogene, KIF22 has been demonstrated to be highly expressed in multiple human cancers." (PMID 37944197, 2023). "Recently, studies have provided insight into the role of KIF22 during cancer progression." (PMID 35436989, 2022). "On the protein level, immunohistochemical results revealed that the staining intensity and positive area of KIF22 in cancer tissues were stronger than those in adjacent tissues, and the staining score of cancer tissues was higher and statistically significant (P < 0.05)." (PMID 35578724, 2022). "KIF22 has been reported essentially for kinds of cancer progression." (PMID 35436989, 2022). "Suppression of KIF22 inhibits cancer cell proliferation through delaying mitotic exit." (PMID 34131588, 2021). "Additionally, we generated inducible retinal pigmented epithelial (RPE-1) cell lines expressing wild-type and mutant KIF22-GFP to assess any differences between the consequences of expressing mutant KIF22 in aneuploid cancer-derived cells (HeLa-Kyoto) and genomically stable somatic cells." (PMID 35730929, 2022). "Data from the PPI network showed that ASPHD1 is related to several proteins and genes such as KIF22, INO80E, SEZ6L2, and DOC2A, most of which are cancer-related." (PMID 37686578, 2023). "We verified the four up-regulated lncRNAs (TCONS_00020615, TCONS_00055555, TCONS_00106091, and TCONS_00130858) and eight cancer-related mRNAs (CDCA3, DIAPH3, MCM7, NCAPG2, TPD52, PRC1, SETD6, and KIF22) involved in the ceRNA network by qRT-PCR." (PMID 37098483, 2023). "Kinesin Family member 22 (KIF22), a Kinesin-like DNA binding protein (KID) belonging to the kinesin-10 family, is considered significant in tumorigenesis and cancer progression." (PMID 37944197, 2023). "Mechanistically, it was observed that in cancer cells independent of KIF22’s microtube-dependent function, KIF22 binds to and transcriptionally represses the promoter region of Cdc25C, an inhibitor of mitosis termination." (PMID 38989461, 2024).
tumor (13 papers, 2010 to 2026). "The findings indicated that high expression of KIF22 was associated with a higher tumor burden in MM and related with poor prognosis." (PMID 38713252, 2024). "Furthermore, changing the expression of KIF22 mainly influenced the cell proliferation in vitro and tumor growth in vivo, and caused G2/M phase cell cycle dysfunction." (PMID 38713252, 2024). "The OE-KIF22 group mice had heavier weight and bigger volume of tumor, and IHC results suggested that KIF22, CDC25C, CD38, and Ki-67 were strongly stained in the OE-KIF22 group." (PMID 38713252, 2024). "Results indicated that the gender (P = 0.016), level of LDH (P < 0.001), β2-MG (P = 0.003), and percentage of tumor cells (BM) (P = 0.002) in MM patients were correlated with the expression of KIF22." (PMID 38713252, 2024). "The results demonstrated that the expression of KIF22 in MM patients was associated with several clinical features, including gender (P = 0.016), LDH (P < 0.001), β2-MG (P = 0.003), percentage of tumor cells (BM) (P = 0.002) and poor prognosis (P < 0.0001)." (PMID 38713252, 2024). "In prostate cancer patients, high KIF22 expression is correlated with tumor development and poor prognosis." (PMID 35436989, 2022). "In the present study we observed a deregulation of both SIAH-1 and Kid/KIF22 proteins in tumor breast tissues, changing from a localized expression to a more diffuse pattern throughout the cell." (PMID 20144232, 2010). "This interaction has been further elucidated through analyzing SIAH and Kid/KIF22 expression in both paired normal and tumor tissues and cell lines." (PMID 20144232, 2010). "In the case of Kid/KIF22, the cellular labeling was also different between each normal tissue sample and its tumor counterpart." (PMID 20144232, 2010). "It revealed that MM patients with high tumor burden had higher expression of KIF22." (PMID 38713252, 2024). "Moreover, the suppression of KIF22 inhibited cell proliferation and xenograft tumor growth." (PMID 37686578, 2023). "Furthermore, in vivo xenograft models confirmed that concurrent knockdown of murine KIF22 and KRAS effectively inhibited tumor progression." (PMID 41727639, 2026).
skeletal dysplasia (4 papers, 2019 to 2024). Any Mendelian diseases that affects growth and development of the skeleton. "Mutations in KIF5B, KIF7, KIF10, and KIF22 kinesin proteins lead to skeletal dysplasia with various severity of clinical features and overlapping phenotypes." (PMID 38646780, 2024).
infection (2 papers, 2020 to 2024). The state of being infected such as from the introduction of a foreign agent such as serum, vaccine, antigenic substance or organism. "Finally, after designing a single RNA interference target for FAM83D and KIF22 to mediate siRNA infection, by conducting high-content screening for 5 uninterrupted days, GFP-expressing cells were enumerated." (PMID 38512482, 2024).
neurodevelopmental disorder (2 papers, 2020 to 2022). A behavioral and cognitive disorder with onset during the developmental period that involves impaired or aberrant development of intellectual, motor, or social functions. "The participants in our study with rare variants in ALDOA, KIF22, TAOK2 and SEZ6L2 did not present with ASD or neurodevelopmental disorders." (PMID 35330733, 2022).
KIF22 also shares sentences with these, for which no sentence is quoted: multiple myeloma (2 papers); spondyloepimetaphyseal dysplasia with joint laxity (2); age-related macular degeneration (1); bladder cancer (1); cervical cancer (1); chondrodysplasia (1); glioblastoma (1); intellectual impairment (1); lymph node metastasis (1); metastatic prostate carcinoma (1); sensorineural hearing loss (1); short rib-polydactyly syndrome (1); triple-negative breast carcinoma (1); viral infection (1).